WDR73 (WD repeat domain 73)
Description:
Component of a multiprotein complex required for the assembly of the RNA endonuclease module of the integrator complex. Associates with INTS9 and INTS11 in the cytoplasm, stabilizing the INTS9-INTS11 heterodimer and blocking the active site of INTS11. BRAT1 then joins the complex and plugs the active site of INTS11, leading to WDR73 release and nuclear import of INTS9 and INTS11.
Synonyms: HSPC264; FLJ14888; GAMOS; GAMOS1
Tractability: PROTAC: ubiquitination databases record sites on it.
Gene: Protein-coding gene on chromosome 15 (84,639,285 to 84,654,343, reverse strand). Ensembl gene ENSG00000177082.
Subcellular location: Cytoplasm; Cytoplasm, cytoskeleton, spindle; Cytoplasm, cytoskeleton, spindle pole; Cleavage furrow
Gene Ontology:
Molecular function: protein binding; protein-macromolecule adaptor activity
Biological process: cytoplasmic microtubule organization; nucleus organization
Cellular component: cleavage furrow; cytoplasm; cytosol; spindle pole; spindle
Genetic constraint (gnomAD): Loss-of-function variants: 17 observed, 26.19 expected, observed/expected ratio (o/e) 0.65, 90% interval 0.44 to 0.97. The upper end of that interval is the gene's LOEUF score, 0.97, which puts it in group 4 of 6, group 1 being the genes least tolerant of losing a copy. Missense variants: 379 observed, 355.09 expected, observed/expected ratio (o/e) 1.07, 90% interval 0.98 to 1.16. Synonymous variants: 156 observed, 136.59 expected, observed/expected ratio (o/e) 1.14, 90% interval 1 to 1.3.
Homologues: Orthologues: chimpanzee WDR73 (99% identical), macaque WDR73 (94% identical), pig WDR73 (81% identical), dog WDR73 (79% identical), mouse Wdr73 (78% identical), rabbit WDR73 (77% identical), guinea pig WDR73 (76% identical), rat Wdr73 (72% identical), tropical clawed frog wdr73 (42% identical), zebrafish wdr73 (39% identical). Paralogues in human: GEMIN5 (20% identical), RBBP4 (16% identical), RBBP7 (16% identical), WDR59 (16% identical), WDR77 (15% identical), GRWD1 (14% identical), PEX7 (13% identical), WDR24 (13% identical), ERCC8 (11% identical).
Diseases named in the same sentence as WDR73 in open-access papers:
WDR73 is named in the same sentence as 16 diseases in open-access papers, as found by Europe PMC text mining. Sharing a sentence is not in itself a finding about the gene and the disease. The quoted sentences say what the papers report.
Galloway-Mowat syndrome (7 papers, 2015 to 2025). Galloway syndrome is characterized by the association of nephrotic syndrome and central nervous system anomalies. "Galloway-Mowat syndrome is caused by mutations in the WDR73 (WD repeat domain 73) gene, which has high levels of expression in the brain, mainly in the cerebellum." (PMID 33917666, 2021). "The term “Galloway-Mowat syndrome 1 (GAMOS1)” is now used for GAMOS caused by mutations in WDR73, and “Galloway-Mowat syndrome 2-5 (GAMOS2-5)” is used for GAMOS with mutations in LAGE3, OSGEP, TP53RK, and TPRKB, respectively." (PMID 30558655, 2018). "Our detailed neuropathological analysis differentiates WDR73-associated NCS from other forms of Galloway-Mowat syndrome and extends the clinical pathological spectrum." (PMID 26070982, 2015). "Wdr73 has been implicated in a human GWAS of periodontitis and in Galloway-Mowat syndrome, a rare autosomal-recessive condition characterized by nephrotic syndrome associated with microcephaly and neurological impairment." (PMID 26694027, 2015). "However, further analysis of this family identified WDR73 to be the most likely causative gene, consistent with Galloway-Mowat syndrome, although ZNF592 may have contributed to the phenotype." (PMID 39152475, 2024). "A Galloway-Mowat syndrome zebrafish model was generated using wdr73 morpholinos." (PMID 33917666, 2021). "We present a rare case of Galloway-Mowat syndrome (GAMOS) in an elderly patient with a WD repeat domain 73 (WDR73) gene deletion." (PMID 40357071, 2025). "Galloway-Mowat syndrome (GAMOS) is a group of rare hereditary diseases by the combination of early onset steroid-resistant nephrotic syndrome (SRNS) and microcephaly with brain anomalies caused by WDR73, LAGE3, OSGEP, TP53RK, TPRKB, GON7, WDR4 or NUP133 mutations." (PMID 36755238, 2023).
microcephaly (6 papers, 2015 to 2023). A congenital or acquired developmental disorder in which the circumference of the head is smaller than normal for the person's age and sex. "Mutations in WDR73 encoding WD repeat domain 73 was described as the cause for Galloway–Mowat syndrome that is characterized with SRNS and microcephaly with brain anomalies." (PMID 29594119, 2018). "Patient 14 is a 15-year-old female referred for seizures, GDD, microcephaly, and corpus callosum and cerebellar atrophy, all compatible with WDR73 deficiency and CA or GMS, even in the absence of any renal issues." (PMID 37510394, 2023). "Very recently, however, WDR73 deficiency was identified in five individuals with GMS presenting with childhood-onset NS, postnatal microcephaly, severe intellectual disability, and homogenous brain magnetic resonance imaging features including cerebellar atrophy." (PMID 27403357, 2016).
Cerebellar atrophy (4 papers, 2016 to 2023). Cerebellar atrophy is defined as a cerebellum with initially normal structures, in a posterior fossa with normal size, which displays enlarged fissures (interfolial spaces) in comparison to the foliae secondary to loss of tissue. "They concluded that the WDR73 mutation is much more common in cerebellar atrophy associated with neurodegenerative diseases and this mutation may not always be associated with renal involvement." (PMID 27403357, 2016). "Cerebellar atrophy is present for all GAMOS1 patients reported so far and is considered a notable predictive feature for diagnosis of the WDR73 mutation." (PMID 30558655, 2018). "In comparison to GMS cases with negative WDR73-mutations, GMS patients with WDR73-mutations present with classical GMS clinical features including cerebellar atrophy, thin corpus callosum, brain-stem hypoplasia, occasional coarse face, late-onset and mostly slow progressive nephrotic syndrome." (PMID 29929488, 2018).
nephrotic syndrome (4 papers, 2015 to 2022). A collection of symptoms that include severe edema, proteinuria, and hypoalbuminemia; it is indicative of renal dysfunction. "These two cases, in conjunction with the findings of a literature review, indicate that OSGEP pathogenic variants are associated with an earlier onset of nephrotic syndrome and shorter life expectancy than WDR73 pathogenic variants." (PMID 30975089, 2019). "However, the pathological and molecular mechanisms of GAMOS1, especially nephrotic syndrome caused by WDR73 deficiency, remain unknown." (PMID 36290302, 2022). "However, the pathological and molecular mechanisms of Galloway–Mowat syndrome, especially nephrotic syndrome caused by WDR73 deficiency, remains unknown." (PMID 36290302, 2022). "Despite these observations providing some insights into the function of WDR73, the regulatory pathway of WDR73, the precise contributions of WDR73 to cell physiological function, and the mechanisms underlying GAMOS, especially nephrotic syndrome caused by WDR73 deficiency, are poorly understood." (PMID 36290302, 2022).
glioma (1 paper, 2015). A benign or malignant brain and spinal cord tumor that arises from glial cells (astrocytes, oligodendrocytes, ependymal cells). "Western blot analysis revealed full-length WDR73 (42 kDa) in human cerebral cortex and cerebellum as well as fibroblasts, astrocytes, and U87 glioma cells." (PMID 26070982, 2015).
glomerulopathy (1 paper, 2016). "Moreover, glomerulopathy associated with the WDR73 mutation occurs in later years (5–12 years of age)." (PMID 27403357, 2016).
neurodegenerative disease (4 papers, 2016 to 2022). A disorder of the central nervous system characterized by gradual and progressive loss of neural tissue and neurologic function. "Patients with WDR73-positive GAMOS are rarely associated with the typical GAMOS phenotype, but rather present with a predominantly infantile-onset neurodegenerative disease with variable renal involvement." (PMID 30558655, 2018).
kidney disease (3 papers, 2019 to 2025). "Our patient had a pathologic variant of WDR73 but presented with an isolated proteinuria, which also lies in the spectrum of renal disease in GAMOS." (PMID 40357071, 2025). "Variant analyses of patients 1 and 2 were performed by targeted massive parallel sequencing using an updated version of our kidney disease gene panel that includes more than 200 genes causative of or associated with inherited kidney diseases (including WDR73, TPRKB, TP53RK, LARGE3, and OSGEP genes)." (PMID 30975089, 2019). "The other sibling who had the same pathologic variant of WDR73 had no renal disease even at seven years." (PMID 40357071, 2025).
cancer (1 paper, 2021). A tumor composed of atypical neoplastic, often pleomorphic cells that invade other tissues. "Ingenuity pathway analysis of the list of genes differentially expressed between Ctrl -EGF and WDR73 KD -EGF conditions, revealed that the category of functions the most significantly enriched in the WDR73 KD -EGF condition was cancer." (PMID 33686175, 2021).
neurological disorder (1 paper, 2021). "Most interestingly, mutations in genes encoding the Integrator subunits INTS1 and INTS8 have been linked to a neurological disorder strikingly reminiscent of that affecting GAMOS patients with WDR73 mutations." (PMID 33686175, 2021).
retinopathy (1 paper, 2018). "Of note, retinopathy was reported previously in association with the c.400_401delAG, p.(Trp136Alafs*2) mutation in the WDR73 gene." (PMID 29929488, 2018).
WDR73 also shares sentences with these, for which no sentence is quoted: Intellectual disability (2 papers); breast carcinoma (1); Galloway-Mowat syndrome 1 (1); injury (1); periodontitis (1).